IGKV3-15 (immunoglobulin kappa variable 3-15)
Description:
V region of the variable domain of immunoglobulin light chains that participates in the antigen recognition. Immunoglobulins, also known as antibodies, are membrane-bound or secreted glycoproteins produced by B lymphocytes. In the recognition phase of humoral immunity, the membrane-bound immunoglobulins serve as receptors which, upon binding of a specific antigen, trigger the clonal expansion and differentiation of B lymphocytes into immunoglobulins-secreting plasma cells. Secreted immunoglobulins mediate the effector phase of humoral immunity, which results in the elimination of bound antigens. The antigen binding site is formed by the variable domain of one heavy chain, together with that of its associated light chain. Thus, each immunoglobulin has two antigen binding sites with remarkable affinity for a particular antigen. The variable domains are assembled by a process called V-(D)-J rearrangement and can then be subjected to somatic hypermutations which, after exposure to antigen and selection, allow affinity maturation for a particular antigen.
Synonyms: IGKV315; L2
Tractability: Antibody: its Gene Ontology location is reachable by antibodies, with high confidence; UniProt places it where antibodies can reach, with medium confidence; UniProt predicts a signal peptide or a membrane-spanning region; the Human Protein Atlas places it where antibodies can reach.
Gene: Immunoglobulin variable (V) gene on chromosome 2 (89,085,177 to 89,085,787, reverse strand). Ensembl gene ENSG00000244437.
Subcellular location: Secreted; Cell membrane
Subcellular location (Human Protein Atlas): Cytosol; Plasma membrane; Predicted to be secreted
Pathways (Reactome):
Immune System: Antigen activates B Cell Receptor (BCR) leading to generation of second messengers; CD22 mediated BCR regulation; Classical antibody-mediated complement activation; FCERI mediated Ca+2 mobilization; FCERI mediated MAPK activation; FCERI mediated NF-kB activation; FCGR activation; Fc epsilon receptor (FCERI) signaling; Immunoregulatory interactions between a Lymphoid and a non-Lymphoid cell; Initial triggering of complement; Regulation of Complement cascade; Regulation of actin dynamics for phagocytic cup formation; Role of LAT2/NTAL/LAB on calcium mobilization; Role of phospholipids in phagocytosis
Disease: FCGR3A-mediated IL10 synthesis; FCGR3A-mediated phagocytosis; Potential therapeutics for SARS
Hemostasis: Cell surface interactions at the vascular wall
Vesicle-mediated transport: Scavenging of heme from plasma
Gene Ontology:
Molecular function: antigen binding
Biological process: immune response
Cellular component: blood microparticle; extracellular region; immunoglobulin complex; plasma membrane
Homologues: Orthologues: mouse Igkv18-36 (67% identical), rat Igkvl13 (65% identical). Paralogues in human: IGKV3D-15 (98% identical), IGKV3OR2-268 (93% identical), IGKV3-11 (91% identical), IGKV3-7 (90% identical), IGKV3D-11 (90% identical), IGKV3-20 (88% identical), IGKV3D-7 (88% identical), IGKV3D-20 (86% identical), IGKV1-5 (72% identical), IGKV1-9 (71% identical), IGKV1D-8 (71% identical), IGKV1-8 (70% identical), and 81 more.
Diseases named in the same sentence as IGKV3-15 in open-access papers:
IGKV3-15 is named in the same sentence as 1 disease in open-access papers, as found by Europe PMC text mining. Sharing a sentence is not in itself a finding about the gene and the disease. The quoted sentences say what the papers report.
Stroke (1 paper, 2024). Sudden impairment of blood flow to a part of the brain due to occlusion or rupture of an artery to the brain. "We found that tissue containing microglia nodules in MS had significant upregulated Ig genes (IGKC, IGHG1, IGHG2, and IGKV3-15) compared to tissue containing stroke nodules." (PMID 38396116, 2024).